PROM1 (prominin 1)
Diseases named in the same sentence as PROM1 in open-access papers (continued):
Sharing a sentence is not in itself a finding about the gene and the disease.
thyroid tumor (1 paper, 2021). A benign or malignant neoplasm affecting the thyroid gland. "PROM1, NRG1, and PROM1 are related to stimulating thyroid epithelium to the progression of a thyroid tumor, and their mutation may interact to promote thyroid tumor differentiation and proliferation." (PMID 33805984, 2021).
vision disorder (1 paper, 2024). Any impairment to the vision. "Our findings underscore the critical role of PROM1 in maintaining the structural integrity and function of photoreceptors, providing valuable insights into the development of OS and the pathophysiology of vision disorders linked to PROM1 mutations." (PMID 38714794, 2024).
tumor (2,493 papers, 2006 to 2026). "CD133 (prominin-1), originally identified in hematopoietic and neuroepithelial stem cells, is associated with increased tumor-initiating capacity, invasiveness, and clonogenicity in OSCC." (PMID 41303421, 2025). "This evidence suggests that EFTUD2 and PROM1 gene expression have significant diagnostic potential in early tumor detection, potentially reflecting the trends in progression." (PMID 40650074, 2025). "In these tumours, high expression of Prominin-1 (also known as CD133) has been associated with rapid cell growth and increased resistance to treatment." (PMID 39316249, 2025). "CD133 (prominin-1) is a membrane-bound glycoprotein on the surface of cancer stem cells (CSCs) that has been associated with poor prognosis, therapy resistance, and tumor recurrence in GBM." (PMID 37754516, 2023). "PROM1 is a stem cell marker that has been linked to tumor-initiating cells and worse clinical outcomes in several human cancers." (PMID 35893227, 2022). "The most widely used biomarker to identify and target colon CSCs is CD133 (prominin 1), a transmembrane protein associated with tumor progression and poor patient outcomes." (PMID 35115900, 2022). "Loss of prom-1 in a gld-1 or gld-2 mutant background resulted in the formation of a synthetic tumor, indicating that PROM-1 acts in parallel with the GLD-1 and GLD-2 pathways." (PMID 36120589, 2022). "Since then, prominin-1 has been considered as a prominent marker associated with tumor development in the field [see the review and references therein]." (PMID 34476215, 2021). "This establishes PROM1 as a tumor cell intrinsic determinant associated with differential patient survival." (PMID 25184684, 2014). "To define the relative levels of expression of the CD133-encoding PROM1 gene in a larger cohort of ESFT we evaluated 48 tumor RNA samples by quantitative RT-PCR." (PMID 20346143, 2010). "And the study found that at the boundary between tumor and peripheral tissue, the bidirectional interaction of ligand-receptor help to maintain the intratumoral structure and the spatial distribution of PROM1+ and CD47+ CSCs; this process is associated with TME remodeling and tumor metastasis." (PMID 36303541, 2022). "Obviously, the cadherin binding related genes including CTNNB1, CDH1, ITGA6, KRT18, and PROM1 were significantly associated with EpCAM, which also implied that EpCAM could play a role in tumor metastasis." (PMID 35517503, 2022). "Encoded by gene PROM1, CD133 has some cell-cycle dependence, and its expression may be promoted in hypoxic environments, a key characteristic of the tumor microenvironment and of the colon." (PMID 34290978, 2021). "Furthermore, the localization of PROM1 within the cell may influence its function, with cytoplasmic expression potentially being associated with increased tumor aggressiveness." (PMID 40650074, 2025). "Literature evidence suggests that elongation factor Tu GTP binding domain containing 2 (EFTUD2) and prominin (PROM1) gene expression have significant diagnostic potential in early tumor detection, potentially reflecting the trends in progression, and may become a novel therapeutic target." (PMID 40650074, 2025). "The expression of CD133 (Prominin-1), which is a surface glycoprotein linked to organ-specific stem cells and another marker for cancer stem cells, was described as a marker of cancer-initiating cells in different tumor types and was an independent predictor of poor prognosis of NSCLC." (PMID 35563313, 2022). "We found that CSCs expressed high levels of tumor stemness genes (PROM1, CD24, CD47, ANPEP, ALDH1A1, OLFM4, and SOX9), and demonstrated a high cancer stemness score, along with activation of the cancer driver genes EGFR and ERBB2." (PMID 39950944, 2025). "EFTUD2 was significantly upregulated in ccRCC, suggesting a potential involvement in tumor progression, while PROM1 was downregulated." (PMID 40650074, 2025).
tumor (continued). "In this study, relapse-associated Scissor+ tumor cells were consistent with previous studies, showing significant upregulation of CSC markers SIX2, PROM1, and NCAM1." (PMID 40098972, 2025). "Depletion of Prom1-positive cells significantly impeded tumor growth and reduced malignant characteristics across various HCC models." (PMID 41221269, 2025). "Her findings indicate that Prom1 marks a subset of proliferative, tumor-propagating cells that possess CSC-like properties within HCC." (PMID 41221269, 2025). "PROM1 is a well-known marker of cancer stem cells (CSCs), a subpopulation of tumor cells that are thought to be drivers of tumor initiation, recurrence, and metastasis." (PMID 40650074, 2025). "Immunohistochemical analysis from the ccRCC validation cohort revealed that EFTUD2 expression is predominantly within the nuclei of tumor cells, while PROM1 is located in the cytoplasm." (PMID 40650074, 2025). "They revealed the connection between TME remodelling and tumour metastasis through the distribution of PROM1+ and CD47+ cancer stem cells, providing new insights for potential tumour interventions." (PMID 39924620, 2025). "In RCC, PROM1 progenitor cells have been observed to differentiate into endothelial cells, promoting vascularization and tumor growth." (PMID 40650074, 2025). "Previous studies have identified SIX2+CITED1+, PROM1+ or NCAM1+ALDH1+ tumor cells as potential CSC-like populations in WT." (PMID 40098972, 2025). "The hypoxic core and associated nutrient gradients promote the expression of CSC-associated transcriptional markers such as SOX2, OCT4, PROM1 (CD133), and NANOG, enabling the study of CSC plasticity and behavior under tumor-like conditions." (PMID 41323785, 2025). "It was found that in hepatocellular carcinoma, Prom1 marks proliferative tumour cells with characteristics of CSCs." (PMID 40665579, 2025). "The membrane glycoprotein CD133 (prominin-1) is widely regarded as the main molecular marker of cancer stem cells, which are the most malignant cell subpopulation within the tumor, responsible for tumor growth and metastasis." (PMID 38927329, 2024). "Single-cell analysis revealed high expression of SPHK1 in tumor cells (SOX2, KRT18) and cancer-associated fibroblasts (COL1A2 and MMP2) and low expression in cancer stem cells (PROM1)." (PMID 39629135, 2024). "CD133, also known as Prominin-1, is a transmembrane glycoprotein that plays a crucial role in tumor recurrence, metastasis, and resistance to chemotherapy and radiation therapy." (PMID 38672078, 2024). "A clinically relevant factor, associated with poor therapeutic outcome and tumor recurrence after Gemcitabine treatment, is the expression of the surface marker CD133, also known as prominin-1." (PMID 39061250, 2024). "A change in the sensitivity of tumor cells to mTOR inhibitors, temsirolimus and everolimus, was also found in HT-29 cells with a complete knockout of the PROM1 gene." (PMID 38139228, 2023). "CD133, also termed prominin-1, is considered a promising prognostic biomarker for a wide range of tumor types." (PMID 38139228, 2023). "As we previously found CD133/Prom1 to mark proliferative tumor-propagating cells, one would expect that more proliferative cells would be more easily subjected to chemotherapy killing." (PMID 38030644, 2023). "Depletion of Prom1+ cells impedes tumor growth and reduces malignant cancer hallmarks in both HCC models." (PMID 38030644, 2023). "At the same time, clusters of tumor cells showed the stable expression of stemness genes (CD44, PROM1) and genes encoding proteins involved in matrix degradation (MMPs)." (PMID 36674951, 2023). "By lineage tracing approach, we recently showed Prom1 in HCC tumors to mark proliferative tumor-propagating cells with cancer stem cell-like properties." (PMID 38030644, 2023). "The CD133 cell membrane glycoprotein, also termed prominin-1, is expressed on some of the tumor cells of both solid and blood malignancies." (PMID 38139228, 2023).
tumor (continued). "This allowed to directly visualize the quiescent Prom1+ or Sox2+ cells within the tumor and characterize their localization in the core or infiltrating edge tumor areas." (PMID 35970913, 2022). "The co-expression of Prom1-Venus-p27 revealed the presence of qProm1 cells across the whole tumor as in tumor core and infiltrating edge." (PMID 35970913, 2022). "CD133 (prominin 1) has been identified as a surface biomarker of tumor-initiating and therapy-resistant GSCs." (PMID 33572835, 2021). "Considering the expression of CSC-related genes CD44 and CD133 (PROM1) the CD44+ sorted cells demonstrated increased expression than the mixed population of OSCC tumor cells." (PMID 34205649, 2021). "The cluster of Differentiation 133 (CD133, prominin-1) has been studied to identify CSCs in different types of tumors and is considered one of the prognostic markers of tumor development." (PMID 35194430, 2021). "Next, we made a query to identify the list of genes that correlated with PROM1 in these tumor types, individually using Bonferroni correction and a p-value < 0.01 for each case." (PMID 31164716, 2020). "In fact, Cluster 1 contained both Prom1+ Afp+ and Prom1–Afp+ cells, suggesting TICs and tumor cells were enriched in this Cluster." (PMID 33173221, 2020). "Secondly, our RNAseq analysis revealed these PROM1+ cells have a unique gene expression profile consistent with their characteristics as LPCs/DRPs or TICs/tumor cells." (PMID 33173221, 2020). "Thirdly, in the DEN-initiated, WAD-promoted liver tumor model, Prom1+ cells gave rise to DRPs and more importantly tumor cells." (PMID 33173221, 2020). "HCC in patients with expression of tumor stem cell markers such as EpCAM, PROM1 and KRT19 tend to be aggressive and chemoresistant." (PMID 33173221, 2020). "Here we show by genetic lineage tracing that PROM1+ cells are derived in part from hepatocytes in AH and become tumor cells in mice with diethyl nitrosamine (DEN)-initiated, Western alcohol diet-promoted liver tumorigenesis." (PMID 33173221, 2020). "To determine the fate of PROM1+ cells in tumor development, we stained the liver sections with visible tumors with anti-GFP and anti-KRT19 antibodies." (PMID 33173221, 2020). "CD133, known as Prominin-1, is independently expressed on the surface of stem cells and various tissue tumor stem cells." (PMID 33584277, 2020). "CD133 (Prominin-1), a pentaspan transmembrane protein expressed in neural stem cells, has been indicated as a marker for tumor-initiating cells." (PMID 31867574, 2019). "In general, epithelial cell lines and tumors were associated with cancer stem cell markers (CD24, ALDH1A1, and PROM1), markers of tumor aggressiveness (MYCL1 and ASCL1), and markers of apoptosis (BCL2 and BCL2L11)." (PMID 28212573, 2017). "Several markers have been defined to isolate GICs from the bulk of the tumor: CD133, encoded by PROM1, CD44, L1CAM or ITGA6." (PMID 29088733, 2017). "Our data for the first time demonstrated that miR‐29a‐3p inhibited laryngocarcinoma cell survival by targeting PROM1, which suggests that miR‐29a‐3p functions as a tumor‐suppressive miRNA." (PMID 28469977, 2017). "A very recent study performing high-throughput analysis of NMIBC revealed a Class 2 tumor that associates with progression, these Class 2 tumors enriched for cancer stem cell markers such as ALDH1A1, ALDH1A2, PROM1, NES and THY1." (PMID 27655672, 2016). "Consistent with a more undifferentiated phenotype, more than 95% of EGFRvIII-activated pEGFRHi tumor cells expressed Prominin-1 on their cell surface." (PMID 27738329, 2016). "Accordingly, transcript levels for seven of these genes were evaluated, with five of them (MEIS1, HOXA3, OTX2, TWIST1, and PROM1) being underexpressed in the tumor samples." (PMID 25908946, 2015). "Regarding tumor tissues, we found that prominin-1 was expressed extensively in AdCC, to a lesser extent in AciCC and PA and only in scattered cells in MEC." (PMID 24911657, 2014).
tumor (continued). "A similar phenomenon was observed for tumor tissues and inflammatory regions of salivary glands in the present study using two anti-prominin-1 (AC133 and 80B258) antibodies on consecutive sections." (PMID 24911657, 2014). "A previous study showed that these cells express the transmembrane glycoprotein prominin-1 (CD133) (a cell-surface marker expressed on normal human neuronal stem cell) and have the ability to initiate new tumor in vivo after xenotransplantation in mice." (PMID 24900981, 2014). "To identify potential angiocrine factors produced by Prom1+ endothelium and responsible for the difference in tumor growth and characteristics, we analyzed FACS-isolated normal CD31+ Prom1+ and CD31+ Prom1− vasculature by Affymetrix microarray." (PMID 23637986, 2013). "The increased tumor burden created by Prom1+ endothelium suggests its function in fostering tumor growth." (PMID 23637986, 2013). "The pentaspan protein CD133 (Prominin-1) is part of the signature of tumour-initiating cells for various cancer entities." (PMID 23150174, 2013). "To avoid in vitro selection bias by extended neurosphere culture, we implanted the same age C57BL/6J mice cells with Prom1+ and Prom1− tumor cells (5,000 cells/mouse) immediately after anti-Prom1 microbead separation." (PMID 23637986, 2013). "Tumors with GFP+ Prom1+ endothelium had larger, more distorted vessels with thickened walls and exhibited increased tumor cell density." (PMID 23637986, 2013). "ß-galactosidase detection showed that some areas in the tumor showed high numbers of Prom1+ cells with other areas mostly devoid of them." (PMID 23637986, 2013). "CD133, also called Prominin-1, has been used as a valuable marker for identification of normal stem cells, progenitor cells, and tumor initiating cells or cancer stem cells (CSC)." (PMID 23437259, 2013). "Mice co-transplanted with proneural tumor sphere cells and Prom1+ endothelium had a significantly increased tumor burden and more vascular proliferation (angiogenesis) than those co-transplanted with Prom1− endothelium." (PMID 23637986, 2013). "Although, recent investigation of a tumor model system further exemplifies a likely relation between the Shh-pathway and prominin-1–positive cells, to uncover the exact details of that in the neural tube requires further examination." (PMID 23723983, 2013). "There appears to be a preferential distribution of Prom1+ cells in the tumor adjacent to the normal brain parenchyma, in the periphery of pseudo-palisading necrosis and in areas of vascular hyperplasia." (PMID 23637986, 2013). "Taken together, Prom1+ endothelium fosters proneural tumor growth, not only by establishing perfused vessels to meet the metabolic needs, but also by relaying stimulatory angiocrine factors." (PMID 23637986, 2013). "Advantage of this treatment over other cancer therapies comes from the fact that 64Cu-ATSM reduced number of CD133+ (prominin-1 positive) cells within tumor." (PMID 22914969, 2012). "HF stem cell markers such as Nuclear factor of activated T-cells, cytoplasmic 1 (NFATc1), CD34 and Prominin-1/CD133 are all known to contribute in regulating epidermal stem cell quiescence, location, proliferation, wound healing and in tumor formation." (PMID 22383956, 2012). "In keeping with the relative levels of transcript expression, only rare CD133+ cells were detected in the PROM1 low case while large numbers of CD133+ cells were apparent in the PROM1 over-expressing tumor." (PMID 20346143, 2010). "One marker consistently reported as a stem cell marker in tumours of differing origins is CD133 (also known as Prominin 1)." (PMID 20502714, 2010). "We demonstrate that the induced GIC population depleted of Prom1-expressing cells form tumor-spheres in culture and transplantable GBM in vivo." (PMID 19718438, 2009).